MYB (MYB proto-oncogene, transcription factor)
Diseases named in the same sentence as MYB in open-access papers (continued):
Sharing a sentence is not in itself a finding about the gene and the disease.
tumor (continued). "The WHO CNS5 classification introduced diffuse astrocytoma, MYB- or MYBL1-altered, as a distinct entity within pediatric-type diffuse LGGs, designating it as a CNS WHO grade I tumor." (PMID 40628732, 2025). "In this study, scRNA‐seq results revealed that the expressions of GLS, PPP1R13L, MYB, and YAP1 were significantly elevated in tumor epithelial cells." (PMID 41152153, 2025). "The transcriptional activator MYB is overexpressed in ACC tumors, leading to pro-tumorigenic cellular processes such as migration, cellular adhesion, cellular proliferation, tumor growth, and angiogenesis." (PMID 39199639, 2024). "When MYB is upregulated, the number of activated cytotoxic CD8+ T cells increase, helping to regulate tumor growth." (PMID 39072320, 2024). "In ACC, genetic translocation of the MYB gene to the transcription factor gene NIFIB has as a result the MYB-NFIB fusion, an oncogene considered to be an important factor for tumor proliferation." (PMID 38929710, 2024). "The ATR inhibitor berzosertib induced apoptosis in MYB-NFIB ACC1 and ACC2 cells and inhibited tumor growth of patient-derived ACC xenografts." (PMID 38835346, 2024). "Mechanistically, metastatic cell lines recruit MYB via NICD to activate MYC, ultimately promoting tumor migration." (PMID 39263605, 2024). "In an in vivo CRC model, the expression of MYB upregulated the Hsp70 isoform GRP78 of the endoplasmic reticulum, leading to unfolded protein response (UPR) and reduced activation of tumor-infiltrating CD8+ T-cells." (PMID 38835346, 2024). "In one tumor with PLAGL1 amplification (#A388), we found separate focal high-level amplification of the GLI2 oncogene on chromosome 2q14.2, and in another tumor with PLAGL1 amplification (#A93), we found focal amplification of MYB on chromosome 6q23.3." (PMID 36437415, 2023). "These neoplasms are frequently categorized based on specific genetic changes such as FGFR1, MYB/MYBL1, BRAF, or IDH1/2, identified through DNA methylation profiles." (PMID 38137148, 2023). "Aberrant MYB expression begins early in preneoplastic HGPIN, increases with advancing tumor grades and pathological stages, exhibits correlative expression with AR, and serves as a better predictor of BCR than nuclear AR and Gleason’s grades." (PMID 38089573, 2023). "Accordingly, we first propose the dual role for NICD1 in SACC, as follows: ATRA-induced upregulation of NICD1 and downregulation of MYB or MYC through RARα alters SACC cell fate differentiation and further inhibits tumor cell malignant progression." (PMID 36879115, 2023). "Second, the overexpression of FRA1 downregulated the expression of the following genes involved in transformation and tumor promotion: WNT9A, AXIN2, and MYB." (PMID 37830558, 2023). "A previous study with linsitinib, crizotinib, and gefitinib that target IGFR1, MET, and EGFR decrease mRNA MYB-NFIB levels or even block protein synthesis, which promote cell differentiation and decrease of tumor growth in vivo and in vitro." (PMID 37476370, 2023). "Inter-Duct 3–4 cells were coregulated by the upstream TFs, MYB, and EN1, which were enriched for tumor progression pathways." (PMID 36465348, 2022). "Our study provides new knowledge about the prevalence and clinical significance of MYB/MYBL1 alterations and indicates the presence of genes with tumor suppressive functions in 6q23.3-qter that contribute to poor prognosis and short overall survival in ACC." (PMID 35954356, 2022).
tumor (continued). "MYB and EN1, as upstream TFs, regulated downstream genes related to domain neural activity together, histone deacetylation, and other tumor processes in Inter-Duct 3–4 cells." (PMID 36465348, 2022). "Of the ten tumors data analyzed, MYB breakpoint occurred at exon 8 for tumors HN332PT, HN348PT, HN325PT and HN312PT, and at exon 15 for tumor samples HN335PT, HN341PT, HN345PT, and HN317PT." (PMID 35565392, 2022). "qRT-PCR data showed that the mRNA levels of BC200 and MYB were downregulated, while miR-150-5p was upregulated in BC200-silenced tumor tissues compared with control tissues." (PMID 35136029, 2022). "It has been reported that detection rate of MYB-NFIB fusion gene in breast ACC is discrepant, related to tumor treatment therapy and detection methods." (PMID 35331206, 2022). "Our study provides new knowledge about the frequency and clinical significance of MYB/MYBL1 alterations and identifies genes with tumor suppressive functions on chromosome 6 that contribute to poor prognosis in ACC." (PMID 35954356, 2022). "We observed significant correlations between the expression levels of the core DEGs SATB-2, ORP-1, MYB, and CDX-2 and tumor immune cell infiltration represented by the expression of B cell, CD4+ T cell, CD8+ T cell, and macrophage markers in TCGA." (PMID 33632198, 2021). "The “classifier” assigned the tumor to the LGG, MYB/MYBL methylation class with a calibrated max-score of 0.99." (PMID 33803647, 2021). "SATB-2, ORP-1, MYB, and CDX-2 were related to cetuximab sensitivity as well as enhanced tumor immune cell infiltration in patients with CRC." (PMID 33632198, 2021). "Previous reports have shown that the tumour suppressor isoform of ZFHX3 (isoform P1) upregulates the expression of the tumour suppressor CDKN1A and downregulates the expression of the oncogene MYB." (PMID 33499898, 2021). "We especially reviewed the relationships between MYBBP1A, the inhibitory role it plays by binding and inactivating c-MYB and its regulation of PGC-1α, leading to an increase in the stemness and the tumor stem cell population." (PMID 31968688, 2020). "Transcriptome analyses showed that TSPX or TSPX[∆C] overexpression downregulated multiple cancer-drivers/oncogenes, including MYC and MYB, in a CAD-dependent manner and upregulated various tumor suppressors in a CAD-independent manner." (PMID 30863497, 2019). "This PGC1α activation suggests the reorientation of tumor cell metabolism toward OXPHOS in MYBBP1A‐downregulated and c‐MYB‐positive cells." (PMID 31066170, 2019). "Nonetheless, they observed elevated expression of KDM4B, XBP1, AR, MYB, and SPDEF in early neoplasias compared to normal which were also elevated in our profile." (PMID 31248446, 2019). "However, reduced amount of TAMs associated with high MYB expression by tumor cells may also arise from altered TAMs proliferation not only recruitment of precursors from circulation." (PMID 31406165, 2019). "We have identified a group of tumor samples that shows low expression of MYBBP1A and high expression of PGC1α and c‐MYB target genes involved in metabolic pathways." (PMID 31066170, 2019). "Whereas, overexpression of ZNF143 reversed the miR-590-3p-mediated tumor-suppressive effects through elevating ASAP3 and MYB expression." (PMID 31186064, 2019). "These shortcomings can limit the detection and annotation of specific MYB-NFIB fusion transcripts and their potential biological function in the context of tumour phenotype and behaviour." (PMID 31301736, 2019). "Using a computational strategy to eliminate genes that were exclusively targeted by the tumor-suppressive miRNAs, they identified the known T-ALL oncogene MYB (target of miR-150, miR-155, and miR-200)." (PMID 29435192, 2018).
tumor (continued). "Gene fusions involving MYB, MYBL1, and NFIB, which were found in nearly 90% of our SAdCC cases, are currently considered to be the primary oncogenetic event in SAdCC, and RAS mutations may confer progressive or invasive features on the tumor cells, resulting in a worse prognosis for SAdCC patients." (PMID 29682203, 2018). "In contrast, the oncogenes MYC and MYB, the expression of which is driven by the WNT pathway in CRC, remained elevated in quiescent and proliferating LGR5+ tumor cell populations." (PMID 28468934, 2017). "To determine whether inherited, CYLD‐defective tumours express MYB–NFIB fusion transcripts, we adopted a validated RT–PCR strategy for exploring the presence of such transcripts in a collection of 13 snap‐frozen and 10 FFPE tumours derived from patients with BSS with confirmed CYLD mutations." (PMID 26969893, 2016). "To identify possible rearrangements of the MYB locus, we performed FISH analysis of FFPE sections from 10 CYLD‐defective tumours (cases 14–23)." (PMID 26969893, 2016). "We observed that forced MYB-NFIB expression in human salivary gland cells alters cell morphology and cell adhesion in vitro and depletion of VCAN blocked tumor cell growth of a short-term ACC tumor culture." (PMID 25587024, 2014). "This indicates the major clinical impact of both MYB and ARNT2 to be tumor suppressive during early tumor development." (PMID 24639887, 2014). "A high-level CCND3 tumor (Case OC-07) showed co-amplification of MYC and AKT2; and a high-level MYC tumor (OC-08) was co-amplified for JAK2, FGFR3, and MYB." (PMID 23289505, 2013). "Studies have demonstrated that abnormalities in AG genomes primarily affect the v-myb avian myeloma virus oncogenic homolog (MYB) gene located at 6q23.3, where MYB genes are normally fused to form the MYB-QKI fusion protein, which is observed in most AG tumor cells." (PMID 39098857, 2025). "Oncogenes such as MYB (myeloblastosis transcription factor), meningioma 1 (MN1), progranulin (PGRN) and amphiregulin (AREG) contribute to abnormal transcriptional activity and tumor progression." (PMID 40628732, 2025). "In the context of this study, MYB is positioned as a key mediator in the miRNA-195-5p-regulated pathway, potentially linking it to the PI3K/AKT/mTOR signaling axis, which is critical for tumor growth and metabolism." (PMID 41141380, 2025). "Activation of genes related to this pathway (CSF2, SERPINE1, PDGFD, CYFIP2, IL7R, MYB, CSF1) can promote tumor cell proliferation and survival, and may also affect immune cells in the TME." (PMID 41328768, 2025). "The tumor exhibited no IDH1, IDH2, TERT, H3, or BRAF mutation, and had no EGFR amplification, no MYB rearrangement, and a positive MGMT status." (PMID 39227460, 2024). "However, in ACC tumor cells, deletion in the 3′ UTR region disrupts its interaction with miRNA, ultimately leading to the overexpression of the MYB gene." (PMID 39263605, 2024). "SCRIPro could accurately predicts well-known master regulators including SPI1, IRF1, FLI1, and STAT2 for mono/macrophages, GATA3, RUNX3, SMARCA4, JUND, and MYB for T-cells, PAX5, BCL2, and IRF4 for B and tumor B-cells." (PMID 39024032, 2024). "They identified all-trans retinoic acid (ATRA) as an inhibitor of endogenous MYB expression, showing that it downregulates the expression of the MYB-NFIB fusion protein in ACC cells in vitro and suppresses tumor growth in ACC patient-derived xenograft models in vivo." (PMID 38542205, 2024). "Previous studies have demonstrated the important tumour-suppressive role of miR-193b-3p, as it targets several members of the RAS-RAF-MEK-ERK pathway which is crucial for cell cycle and proliferation, as well as c-KIT and the MYB oncogene." (PMID 39796140, 2024). "Moreover, Pearson correlation showed a significant relationship between the expression levels of MYB and BUB1 in patient tumours." (PMID 38112379, 2024).
tumor (continued). "Evidence suggests that, regardless of age, MYB-/MYBL1-altered diffuse gliomas typically behave as WHO grade 1 neoplasms and are generally indolent." (PMID 38544524, 2024). "In contrast, the MYB-NFIB fusion is not expressed in non-adenoid cystic carcinoma neoplasms of the head and neck, confirming the high specificity of the MYB-NFIB fusion, which has been used as a diagnostic marker for ACC." (PMID 37152992, 2023). "Due to the existence of several routes for overexpression, such as selective gain at MYB locus, upregulation of the gene can be seen in both fusion-positive and a subset of fusion-negative tumours." (PMID 37762061, 2023). "We finally evaluated MYB-NFIB expression system and its capacity to promote tumor growth in vivo." (PMID 35565392, 2022). "Five tumours were classified as “LGG, MYB/MYBL” by DNA methylation profiling." (PMID 35836307, 2022). "In addition, the expression of these IRGs can be regulated by the transcription factors MYB, SP1, and SP3, which are related to tumor immunity." (PMID 35463955, 2022). "Accordingly, future studies are warranted to further investigate the detailed molecular mechanisms of the combined treatment with BBR and OPCs on MYB and PI3K-Akt signaling pathway, including the validation of our findings in the tumor spheroids and animal models." (PMID 35600365, 2022). "Taken together, our study provides new knowledge about the prevalence and clinical significance of MYB and MYBL1 alterations in ACC and indicates the presence of genes with tumor suppressive functions in 6q23.3-qter that contribute to poor prognosis in a subset of tumors." (PMID 35954356, 2022). "Molecular pathology analysis by fluorescence in situ hybridization revealed that the tumor was negative for MYB rearrangements." (PMID 35875113, 2022). "Western bot analysis was also done to confirm the MYB protein expression in HCC tissue samples, the results of representative cases showed that NTT overexpression upregulated the expression of MYB, and NTT downexpression downregulated the expression of MYB in the paired normal and tumor tissues." (PMID 34616668, 2021). "Furthermore, Western blot analysis was employed to examine the protein expression patterns of MYB and VEGF in tumor tissues of nude mice after different treatments." (PMID 33407591, 2021). "Mechanistically, combined with KEGG pathways analysis, our data showed that overexpressed LOC102724169 could decrease MYB by attenuating the PI3K/AKT pathway to enhance cisplatin chemosensitivity and exert an anti-tumor effect in OCCS." (PMID 33850634, 2021). "When MYB is suppressed, the overexpression of miR-1258 inhibits the expression of GRB2 and then inactivates the carcinogenic pathway of Ras/ERK, which then induces senescence and apoptosis of tumor cells." (PMID 34876130, 2021). "Our studies thus identify a novel link between MYB and ATR in ACC that may have implications also for other types of neoplasms with activation of the MYB oncogene." (PMID 32001675, 2020). "No tumors were detected after a latency period of 5 months, indicating that stable MYB or MYB-NFIB overexpression is not sufficient for tumor formation of MCF10A cells (data not shown)." (PMID 32001675, 2020). "MiR-29a and miR-150 were both shown to be tumor suppressors that, respectively, sensitized NPM-ALK(+) ALCL cells to doxorubicin-induced apoptosis through MCL-1 targeting, and reduced cell growth and viability through MYB." (PMID 29581862, 2018). "Nevertheless, the molecular mechanism of how the critical oncogenic driver MYB influences tumor progression has not yet been fully elucidated." (PMID 30206227, 2018). "For ACC11, SKY revealed new translocations along with the 6:9 translocation for MYB-NFIB that were not known for this tumor and were also present in all metaphase nuclei." (PMID 28900283, 2017). "Whilst 55% of the tumours were fusion‐positive, some tumours (12%) demonstrated MYB activation despite the lack of fusion transcripts." (PMID 26969893, 2016).
tumor (continued). "We explored the expression of MYB and selected MYB target genes following their curation from the published literature and previous experimental data from 32 CYLD‐defective tumours 7, in a dataset derived from microarray gene expression studies (no. of transcripts in this set = 263)." (PMID 26969893, 2016). "Strikingly, none of the inherited CYLD‐defective (n = 23) tumours expressed MYB–NFIB fusion transcripts." (PMID 26969893, 2016). "Furthermore, we found that 4EGI-1 selectively inhibits translation of mRNAs encoding proteins that are enhanced in CSC maintenance, proliferation and metastasis, such as NANOG, OCT4, c-MYC, cyclin D1, CXCR4, VEGF and c-MYB, in breast CSC tumor cells." (PMID 25115391, 2014). "In contrast, ROBO1 disconnects N-cadherin from the cytoskeleton in invasive cells, thus increasing their motility; c-MYB induces expression of MGMT, resulting in higher chemoresistance; expression of SOX2 and OLIG2 result in greater stemness and higher capacity for tumour formation." (PMID 23818228, 2013). "Results were available for twelve of fourteen patients; 83.3% (n = 10) of the tumors analyzed displayed MYB rearrangements at the 6q23.3 locus; 75% (n = 9) had NFIB rearrangements, and 17% (n = 2) of tumor samples did not have rearrangements of MYB or NFIB genes on FISH analysis." (PMID 39199639, 2024). "Furthermore, both patients with a diagnosis of lacrimal gland ACC in our study possessed this gene fusion; 69.2% of patients had NFIB rearrangements, and 15.4% of tumor samples did not have rearrangements of MYB or NFIB genes on FISH analysis." (PMID 39199639, 2024). "Furthermore, treatment with an ATR kinase inhibitor (VX-970) induced programmed cell death in ACC cells that are MYB-positive and also significantly decreased cellular proliferation rates and inhibited ACC tumour growth, with one mouse demonstrating tumour regression." (PMID 37762061, 2023). "As a main member of MYB gene family which includes MYB, MYBL1 and MYBL2, MYB is involved in the control of cell survival, proliferation and differentiation and, as a transcription factor, serves as a convergence of numerous signaling pathways, which is essential for tumor progression." (PMID 36994664, 2023). "In a recent study it has been proposed that negative immunostaining for MYB may identify tumours with poorer prognosis." (PMID 35397067, 2022). "Finally, we sought to evaluate whether MYB-NFIB fusion expression is permissive to form and support tumor growth in vivo." (PMID 35565392, 2022). "The expression of CTGF and MYB was significantly higher in HCC tissues than that in the adjacent non-tumor tissues (p < 0.05), while the expression of BCLAF1, IFNGR1, and HIVEP2 was significantly lower in HCC tissues than in adjacent non-tumor tissues (p < 0.05)." (PMID 34616668, 2021). "However, when injected into the flank of immunodeficient mice no tumors were detected after a latency period of 5 months, indicating that stable MYB or MYB-NFIB overexpression is not sufficient for tumor formation of MCF10A cells." (PMID 32001675, 2020). "An MYB-NFIB and MYB-split-positive status had no or only a weak clinicopathological impact whereas an MYB/MYBL1-split-positive status was associated with a higher tumor grade and a local aggressiveness of the tumor but failed to have a prognostic impact." (PMID 29682203, 2018). "Similarly to the haemopoietic and colonic epithelial cell systems, decreased MYB expression on differentiation is not limited to tumor cell lines, as we have shown here for the non-tumorigenic murine MEC line HC11." (PMID 20659323, 2010). "Interestingly, ACC tumor samples with mutations in NOTCH1 and SPEN had no alterations in MYB and MYBL1, suggesting that other genetic events than alterations in MYB/MYBL1 may also play a central role in developing the ACC." (PMID 37476370, 2023).